KIAA1143 (KIAA1143)
Tractability: PROTAC: ubiquitination databases record sites on it; its protein half-life has been measured.
Gene: Protein-coding gene on chromosome 3 (44,737,661 to 44,762,033, reverse strand). Ensembl gene ENSG00000163807.
Subcellular location (Human Protein Atlas): Nucleoplasm; Cytokinetic bridge
Gene Ontology:
Molecular function: protein binding
Cellular component: intercellular bridge; nucleoplasm
Genetic constraint (gnomAD): Loss-of-function variants: 4 observed, 10.25 expected, observed/expected ratio (o/e) 0.39, 90% interval 0.19 to 0.89. The upper end of that interval is the gene's LOEUF score, 0.89, which puts it in group 3 of 6, group 1 being the genes least tolerant of losing a copy. Missense variants: 110 observed, 109.41 expected, observed/expected ratio (o/e) 1.01, 90% interval 0.86 to 1.18. Synonymous variants: 44 observed, 40.54 expected, observed/expected ratio (o/e) 1.09, 90% interval 0.85 to 1.39.
Homologues: Orthologues: chimpanzee KIAA1143 (100% identical), macaque KIAA1143 (97% identical), pig KIAA1143 (92% identical), dog KIAA1143 (90% identical), rabbit KIAA1143 (90% identical), mouse 1110059G10Rik (88% identical), guinea pig KIAA1143 (88% identical), rat RGD1311745 (88% identical), tropical clawed frog KIAA1143 (60% identical), zebrafish zgc:77056 (53% identical), Drosophila melanogaster CG42245 (42% identical), Caenorhabditis elegans T25G3.1 (38% identical).